SAMD15 (sterile alpha motif domain containing 15)
Synonyms: C14orf174; FAM15A; FLJ35963
Tractability: No criterion of Open Targets' tractability assessment is met for any kind of drug.
Gene: Protein-coding gene on chromosome 14 (77,376,689 to 77,392,163, forward strand). Ensembl gene ENSG00000100583.
Subcellular location (Human Protein Atlas): Nuclear membrane; Nucleoplasm; Cytosol; Nucleoli
Gene Ontology:
Molecular function: protein serine/threonine kinase activator activity
Biological process: signal transduction
Genetic constraint (gnomAD): Loss-of-function variants: 33 observed, 47.75 expected, observed/expected ratio (o/e) 0.69, 90% interval 0.52 to 0.92. The upper end of that interval is the gene's LOEUF score, 0.92, which puts it in group 3 of 6, group 1 being the genes least tolerant of losing a copy. Missense variants: 769 observed, 805.59 expected, observed/expected ratio (o/e) 0.95, 90% interval 0.9 to 1.01. Synonymous variants: 252 observed, 293.7 expected, observed/expected ratio (o/e) 0.86, 90% interval 0.77 to 0.95.
Homologues: Orthologues: chimpanzee SAMD15 (97% identical), macaque SAMD15 (90% identical), mouse Samd15 (38% identical), rat Samd15 (27% identical), dog SAMD15 (11% identical), tropical clawed frog samd15 (10% identical), Drosophila melanogaster CG12592 (9% identical), Drosophila melanogaster Cp190 (8% identical), Drosophila melanogaster CG9915 (5% identical), Caenorhabditis elegans F13B12.1 (4% identical). Paralogues in human: MDN1 (22% identical), TCHHL1 (12% identical), IWS1 (11% identical).